PKD1-AS1 (PKD1 antisense RNA 1)
Synonyms: LUCRC
Gene: Long non-coding RNA gene on chromosome 16 (2,091,436 to 2,095,433, forward strand). Ensembl gene ENSG00000259933.
Diseases named in the same sentence as PKD1-AS1 in open-access papers:
PKD1-AS1 is named in the same sentence as 3 diseases in open-access papers, as found by Europe PMC text mining. Sharing a sentence is not in itself a finding about the gene and the disease.
PKD1-AS1 shares sentences with these, for which no sentence is quoted: tumor (2 papers); colorectal cancer (1); colorectal tumor (1).